PSAP (prosaposin)
Description:
Saposins are specific low-molecular mass non-enzymatic glycoproteins that act as activator proteins for lysosomal sphingolipid-degrading enzymes, facilitating the hydrolysis of sphingolipids by extracting lipid substrates from membranes and presenting them to their respective enzymes. They are derived from a common precursor protein, prosaposin, which is proteolytically cleaved to yield four homologous proteins (saposin A, B, C, and D), each with distinct but partially overlapping lipid and enzyme specificities. [Prosaposin]: Behaves as a myelinotrophic and neurotrophic factor, these effects are mediated by its G protein-coupled receptors, GPR37 and GPR37L1, undergoing ligand-mediated internalization followed by ERK phosphorylation signaling. [Saposin-A]: acts as an essential lysosomal cofactor that activates galactocerebrosidase (GALC, EC 3.2.1.46) by facilitating enzyme access to its membrane-embedded galactosylceramide substrate, the principal lipid component of myelin. [Saposin-B]: Stimulates the hydrolysis of galacto-cerebroside sulfate by arylsulfatase A ARSA (EC 3.1.6.8), GM1 gangliosides by beta-galactosidase (EC 3.2.1.23) and globotriaosylceramide by alpha-galactosidase A (EC 3.2.1.22). Forms a solubilizing complex with the substrates of the sphingolipid hydrolases. [Saposin-C]: Acts as an essential lysosomal cofactor that activates acid beta-glucosylceramidases (EC 3.2.1.45) by altering lipid bilayer properties to facilitate enzyme access to its membrane-embedded glucosylceramide substrate, while also protecting glucocerebrosidase from intralysosomal proteolytic degradation. [Saposin-D]: Acts as a lysosomal activator protein that stimulates acid ceramidase (EC 3.5.1.23) by solubilizing and presenting ceramide substrates at the lipid-water interface, facilitating their hydrolysis into sphingosine and fatty acids. It also activates acid sphingomyelinase (EC 3.1.4.12), though ceramide catabolism represents its primary physiological role.
Synonyms: GLBA; SAP1; PARK24; PSAPD; SAP2
Tractability: Small molecule: a structure with a bound ligand is known; it has a high-quality binding pocket. Antibody: its Gene Ontology location is reachable by antibodies, with high confidence; UniProt places it where antibodies can reach, with medium confidence; UniProt predicts a signal peptide or a membrane-spanning region. PROTAC: ubiquitination databases record sites on it; its protein half-life has been measured; a small molecule that binds it is known.
Gene: Protein-coding gene on chromosome 10 (71,816,289 to 71,851,330, reverse strand). Ensembl gene ENSG00000197746.
Subcellular location: Lysosome; Secreted (Prosaposin)
Subcellular location (Human Protein Atlas): Vesicles
Pathways (Reactome):
Signal Transduction: G alpha (i) signalling events; Peptide ligand-binding receptors
Hemostasis: Platelet degranulation
Immune System: Neutrophil degranulation
Metabolism: Glycosphingolipid catabolism
Gene Ontology:
Molecular function: ganglioside GM1 binding; ganglioside GM2 binding; ganglioside GM3 binding; ganglioside GP1c binding; ganglioside GT1b binding; phospholipid binding; protease binding; protein binding; protein homodimerization activity; scaffold protein binding; identical protein binding; lipid binding
Biological process: ganglioside GM1 transport to membrane; gene expression; lysosomal transport; adenylate cyclase-inhibiting G protein-coupled receptor signaling pathway; epithelial cell differentiation involved in prostate gland development; prostate gland growth; regulation of autophagy; regulation of lipid metabolic process; lipid metabolic process; sphingolipid metabolic process
Cellular component: extracellular exosome; extracellular region; late endosome; lysosome; azurophil granule membrane; lysosomal lumen; lysosomal membrane; plasma membrane
Genetic constraint (gnomAD): Loss-of-function variants: 25 observed, 68.86 expected, observed/expected ratio (o/e) 0.36, 90% interval 0.26 to 0.51. The upper end of that interval is the gene's LOEUF score, 0.51, which puts it in group 2 of 6, group 1 being the genes least tolerant of losing a copy. Missense variants: 649 observed, 702.71 expected, observed/expected ratio (o/e) 0.92, 90% interval 0.87 to 0.99. Synonymous variants: 273 observed, 270.71 expected, observed/expected ratio (o/e) 1.01, 90% interval 0.91 to 1.12.
Gene-disease validity (ClinGen):
ClinGen rates the evidence that PSAP causes each of these diseases.
combined PSAP deficiency (autosomal recessive): Definitive. Encephalopathy due to prosaposin deficiency is a lysosomal storage disease belonging to the group of sphingolipidoses.
Gaucher disease due to saposin C deficiency (autosomal recessive): Definitive. Any Gaucher disease in which the cause of the disease is a mutation in the PSAP gene.
Krabbe disease due to saposin A deficiency (autosomal recessive): Moderate.
Homologues: Orthologues: chimpanzee PSAP (99% identical), macaque PSAP (99% identical), pig PSAP (85% identical), dog PSAP (85% identical), guinea pig PSAP (76% identical), rat Psap (70% identical), mouse Psap (68% identical), rabbit PSAP (64% identical), zebrafish psap (46% identical), tropical clawed frog psap (44% identical). Paralogues in human: PSAPL1 (44% identical), SFTPB (19% identical).
Diseases named in the same sentence as PSAP in open-access papers:
PSAP is named in the same sentence as 141 diseases in open-access papers, as found by Europe PMC text mining. Sharing a sentence is not in itself a finding about the gene and the disease. The quoted sentences say what the papers report.
Gaucher disease (21 papers, 2011 to 2026). Gaucher disease (GD) is a lysosomal storage disorder encompassing three main forms (types 1, 2 and 3), a fetal form and a variant with cardiac involvement (Gaucher disease - ophthalmoplegia - cardiovascular calcification or Gaucher-like disease). "PSAP variants are linked to multiple neurodegenerative diseases, including synucleinopathies, Gaucher's disease, and metachromatic leukodystrophy." (PMID 41627451, 2026). "The responsible gene is GBA1, although less frequently, Gaucher disease can be attributed to mutations in the prosaposin gene that codes for an activator (saposin C) of the lysosomal protein β-glucosidase acid." (PMID 40332757, 2025). "In conclusion, we identified a new likely pathogenic missense variant in PSAP in a large consanguineous Pakistani family with atypical Gaucher disease." (PMID 35456468, 2022). "The authors concluded that the biallelic mutations of the PSAP gene are the cause of the patient’s Gaucher disease." (PMID 30781349, 2019). "Deficiency in PSAP or individual SAPs leads to several lysosomal storage disorders including Gaucher disease, Krabbe disease, and metachromatic leukodystrophy." (PMID 28828399, 2017). "Atypical Gaucher disease is caused by variants in the PSAP gene." (PMID 35456468, 2022). "Also, in rare cases, atypical Gaucher disease is due to saposin C deficiency (transporter protein), which results from biallelic variants in the PSAP gene, enzyme estimation in blood might not be informative." (PMID 37383036, 2023). "This review examines current research on the functional and pathological roles of PSAP, emphasizing the importance of PSAP in Gaucher disease, neurodegenerative diseases, cardiovascular diseases, and cancer." (PMID 40801564, 2025). "Saposin C is required for GCase activity, and thus mutations in PSAP that lead to saposin C deficiency also cause Gaucher disease." (PMID 29233882, 2017). "In Gaucher disease (GD), PSAP-derived Sap C is critical for glucocerebrosidase (GCase, also known as glucose ceramidase or acid β-glucosidase, EC: 4.2.1.25) activity and stability, and its defects lead to a decrease in GCase function, which in turn triggers neurological lesions." (PMID 40801564, 2025). "Gaucher disease is most frequently caused by mutations in the GBA1 gene which encodes GCase; however, there are rare cases of Gaucher disease caused instead by mutations in the PSAP gene." (PMID 29233882, 2017). "In Gaucher disease, variants in the SCARB2 or PSAP may modulate neurological involvement." (PMID 41567994, 2026).
prostate carcinoma (19 papers, 2004 to 2024). A carcinoma that arises from epithelial cells of the prostate gland. "PSAP protein levels have been implicated with prostate cancer progression, with PSAP being amplified in metastatic androgen-independent prostate cancer cells and possibly a role in carcinogenesis." (PMID 29929489, 2018). "The specificity for the distinction of prostate cancer was somewhat lower for prostein (91.7%) as compared to the 100% for PSAP and PSA (99.7%) observed in these earlier studies." (PMID 38218896, 2024). "This identified 60 glycopeptides as potential substrates for GCNT1 in prostate cancer cells, including a potential increase in core 2 O-glycan structures on PSAP and MUC16." (PMID 37813880, 2023). "Examples include circ0005276 in prostate cancer cells through the activation of X-linked inhibitor of apoptosis protein (XIAP) and circVAPA in HCC cells through the activation of prosaposin (PSAP)." (PMID 34162394, 2021). "In prostate cancer cell, downregulation of PSAP decreased b1A-integrin expression, its cell-surface clustering, and adhesion to basement membrane proteins." (PMID 33119648, 2020). "Previous work using a KLK3 promoter/GFP reporter (PSAP-eGFP) showed that LNCaP prostate cancer cells display varying levels of eGFP expression." (PMID 30644358, 2019). "It was reported that prosaposin down-modulation decreases metastatic prostate cancer cell adhesion, migration, and invasion." (PMID 27036049, 2016). "The exosomal (CD9- CD81-SCARB2) (average enrichment 2.40) and lysosomal (CTSD- LAMP2- CTSZ- SPNS1- PSAP) (average enrichment 4.15) proteins were also enriched in exosomes from prostate cancer patients." (PMID 26196085, 2015). "A previous report demonstrated that prosaposin down-modulation decreases metastatic prostate cancer cell adhesion, migration, and invasion." (PMID 23717685, 2013). "We have recently reported a higher expression of prosaposin in androgen-independent (AI) prostate cancer cells (PC-3 and DU-145) than in androgen-sensitive (AS) LNCaP or in normal prostate epithelial and stromal cells." (PMID 15548330, 2004). "We have recently reported that prosaposin is expressed at a higher level by androgen-independent (AI) prostate cancer cells as compared to androgen-sensitive prostate cancer cells or normal prostate epithelial and stromal cells." (PMID 15548330, 2004). "This hypothesis was born out by the observations that PRSS2 expression negatively correlates with PSAP expression in prostate cancer." (PMID 36575174, 2022). "On the contrary, another study has suggested the involvement of PSAP in prostate cancer invasion." (PMID 36359323, 2022). "PSAP has been previously reported to induce AR protein in prostate cancer cells." (PMID 26341737, 2015). "PSAP has previously been reported to activate androgen receptor (AR) in prostate cancer cells." (PMID 26341737, 2015). "These were 7 tests for h-caldesmon (for leiomyosarcoma), 3 CDK4 (for WDL/DDL), 2 DOG1 (for GIST), 2 beta-catenin (for fibromatosis), 1 each of CD34 (DFSP), desmin, myogenin (rhabdomyosarcoma (RMS)), p63 (sarcomatoid carcinoma), PSAP (prostatic carcinoma), and TLE1 (synovial sarcoma)." (PMID 25165418, 2014). "We postulate that as a mitogenic, survival, and anti-apoptotic factor for prostate cancer cells, saposin C or prosaposin may contribute to prostate carcinogenesis at its early androgen-dependent or metastatic AI state." (PMID 15548330, 2004). "Finally, our observations provide novel insights into the diversity of biological activities of prosaposin in prostate cancer cells." (PMID 15548330, 2004). "Paradoxically, high PSAP levels are associated with weakly- or non-metastatic prostate cancers, a reduction in distant metastasis and PSAP serum levels are elevated in advanced-stage prostate cancer patients." (PMID 32635403, 2020).
prostate carcinoma (continued). "Furthermore, the serum-PSAP levels are increased in patients with advanced prostate cancer and this could provide a cell survival response after therapeutic interventions." (PMID 32526853, 2020). "Accordingly, the sensitivity of PSAP (96.5%) and PSA (99.8%) were slightly higher in previous studies of our group analyzing large consecutive prostate cancer cohorts including much higher proportions of Gleason 3 + 3 and 3 + 4 cancer than in the current set of tumors." (PMID 38218896, 2024). "In addition, we have demonstrated that a synthetic peptide (prosaptide TX14A), derived from the trophic sequence of the saposin C domain of prosaposin, stimulated cell proliferation, migration and invasion and activated the MAPK signaling pathway in prostate cancer cells." (PMID 15548330, 2004).
metachromatic leukodystrophy (18 papers, 2009 to 2026). A rare lysosomal storage disorder characterized by intralysosomal accumulation of sulfatides in various tissues, leading to progressive deterioration of motor and neurocognitive function. "Metachromatic leukodystrophy is an autosomal recessive disorder caused by mutations in the arylsulfatase gene (ARSA) or rarely in the prosaposin (PSAP) gene." (PMID 35976293, 2022). "Metachromatic leukodystrophy (MLD) is an inherited genetic lysosomal storage disease caused by dysfunction of arylsulfatase A (ARSA) or its activator prosaposin (PSAP)." (PMID 38916435, 2025). "Metachromatic leukodystrophy (MLD) due to Sap‐B deficiency is a rare autosomal recessive disorder caused due to biallelic variants in the PSAP gene." (PMID 37404680, 2023). "Deficiency of arylsulfatase A (ARSA) (EC 3.1.6.8) (also due to pathogenic variants in ARSA or PSAP revealing metachromatic leukodystrophy [MLD; OMIM #250100] or SAP‐B deficiency [SAP‐B; OMIM #249900]) leads to accumulation of sulfatides causing neurodegeneration." (PMID 33728250, 2021). "Metachromatic leukodystrophy (MLD) is a rare inherited lysosomal disorder caused by recessive gene mutations in ARSA (OMIM: 607574) and PSAP (Kihara, 1982; Kihara, Fluharty, O'Brien, & Fish, 1982; van Rappard, Boelens, & Wolf, 2015; Schielen, Kemper, & Gelb, 2017)." (PMID 32875726, 2020). "We report on two new patients with PSAP gene defects; one, with pSap-d, who had a severe neurovisceral dystrophy and died as a neonate, and the other with SapB-d, who presented with a metachromatic leukodystrophy-like disorder but had normal arylsulfatase activity." (PMID 19267410, 2009). "In four patients, rare heterozygous RDVs were detected in other neurodegeneration-associated genes, such as PRKN (PD), LRRK2 (PD), PARK7 (PD), C19ORF12 (NBIA), SPG11 (Spastic paraplegia-SP/ALS), and PSAP (Metachromatic leukodystrophy-MLD)." (PMID 35752680, 2022).
lysosomal storage disorders (14 papers, 2011 to 2025). "FTD-GRN brains and iPSC-derived neurons with GRN mutations demonstrate impaired processing of PSAP to saposin C (a critical activator of GCase), resulting in reduced GCase activity, providing insight into the link with lysosomal storage disorders." (PMID 40234992, 2025). "Deficiency in full-length PSAP or individual Saps (by truncation, inactivating mutations, or reduced expression) lead to various lysosomal storage disorders, with neuropathology and often dysfunction of other organs." (PMID 39713930, 2024). "Complete loss of PSAP or the individual saposins has been shown to cause lysosomal storage disorders." (PMID 27356620, 2016). "Therefore, deficiency of PSAP or any saposin is linked to abnormal accumulation of glycosphingolipid in lysosomes, which causes lysosomal storage diseases." (PMID 36359323, 2022). "Finally, in addition to GRN, we found upregulation of other lysosomal genes frequently dysregulated in lysosomal storage disorders such as NEU1, NPC2, PSAP, CTSD, LAMP1, and HEXA." (PMID 38643236, 2024).
breast cancer (12 papers, 2010 to 2025). A primary or metastatic malignant neoplasm involving the breast. "PSAP expression associates with poor prognosis in grade I breast cancer but improved prognosis in grade III." (PMID 40801564, 2025). "The upregulation of PSAP gene expression by HOXC11 in endocrine-resistant breast cancer cells was of interest primarily due to its association with tamoxifen resistance, but also because of its potential as an AR activator." (PMID 26341737, 2015). "In a cohort of breast cancer patients (n = 34), elevated serum levels of PSAP were found to associate significantly with poor response to endocrine treatment (p = 0.04)." (PMID 26341737, 2015). "Western blot analysis of a range of cell lines was performed to evaluate if there is an association between elevated levels of PSAP and nuclear AR protein in breast cancer cells." (PMID 26341737, 2015). "PSAP was also identified as a gene with causative role during functional screening for tamoxifen-resistance in breast cancer cell line, ZR-75-1." (PMID 20132547, 2010). "ECM stiffness induces mesenchymal stem cells (MSCs) to differentiate into CAFs via mechanosignaling, promoting breast cancer cell proliferation/survival but inhibiting metastasis, partly through PSAP-activated Akt signaling." (PMID 40801564, 2025). "Gene expression analysis revealed that PSAP is a direct target of miR-24 and miR-27b, and its expression was negatively correlated with metastatic progression in patients with breast cancer." (PMID 40801564, 2025). "Ectopic PSAP expression inhibits metastasis in aggressive breast cancer cells, even those overexpressing miR-23b/27b/24." (PMID 40801564, 2025). "Mesenchymal stem cells differentiated into CAFs on a stiff matrix secrete the soluble factor prosaposin, which promotes the proliferation of mammary cancer cells." (PMID 35205794, 2022). "For example, a stiff matrix induces EMT, invasion and metastasis in mammary cancer, whereas it prevents metastasis by triggering prosaposin secretion from stromal cells." (PMID 35205794, 2022). "In particular, in breast cancer, mesenchymal stem cells induces prosaposin secretion to drive the proliferation." (PMID 32526853, 2020). "The clinical potential of PSAP is highlighted by the significantly elevated levels of the protein detected in serum from breast cancer patients who experienced disease recurrence on endocrine therapy." (PMID 26341737, 2015). "Here, we demonstrate that stimulation with PSAP can drive AR recruitment to a hormone response element (HRE) in AI resistant breast cancer cells." (PMID 26341737, 2015). "HOXC11 and PSAP mRNA levels are strongly correlated in a primary breast cancer cohort (rs = 0.7692, n = 51)." (PMID 26341737, 2015). "Meta-analysis of combined PSAP and AR mRNA are indicative of poor disease-free survival in endocrine treated breast cancer patients (hazard ratio (HR): 2.2, P = 0.0003, n = 661)." (PMID 26341737, 2015). "In our AI-resistant breast cancer model we have shown that PSAP is capable of upregulating and activating AR in the context of high HOXC11 expression." (PMID 26341737, 2015). "Further analysis of TCGA datasets also demonstrate a correlation between HOXC11 and PSAP transcript levels, specifically in luminal B breast cancer in which AR is elevated (rs = 0.46)." (PMID 26341737, 2015). "Validation and functional evaluation of the target gene, prosaposin (PSAP), was performed in a panel of endocrine sensitive and resistant breast cancer cell lines." (PMID 26341737, 2015). "We then evaluated the impact of PSAP transcript levels on endocrine-treated breast cancer patient outcome using the Breastmark meta-analysis software." (PMID 26341737, 2015). "For example, in breast cancer, PSAP may promote cancer progression by enhancing the Estrogen Receptor α (Erα)-mediated signaling axis." (PMID 40801564, 2025).